CAPN2 (calpain 2)
Diseases named in the same sentence as CAPN2 in open-access papers (continued):
Sharing a sentence is not in itself a finding about the gene and the disease.
inflammatory breast carcinoma (1 paper, 2016). An advanced, invasive breast adenocarcinoma characterized by the presence of distinct changes in the overlying skin. "Low calpain-1 expression was associated with adverse survival in inflammatory breast cancer cases (P=0.003) and low calpain-2 was associated with adverse survival in the non-inflammatory breast cancer cases (P=0.031)." (PMID 27323818, 2016). "In addition, low calpain-2 expression was associated with adverse survival in non-inflammatory breast cancer patients and low calpain-1 expression was associated with adverse survival in inflammatory breast cancer patients." (PMID 27323818, 2016).
invasive breast carcinoma (1 paper, 2016). A carcinoma that infiltrates the breast parenchyma. "In early invasive breast cancer expression of calpain-1, calpain-2 and their inhibitor, calpastatin, have been associated with clinical outcome and clinicopathological factors." (PMID 27323818, 2016).
limb-girdle muscular dystrophy (1 paper, 2023). Limb-girdle muscular dystrophy (LGMD) is a heterogeneous group of muscular dystrophies characterized by proximal weakness affecting the pelvic and shoulder girdles. "Humans have three clp-4 orthologs, CAPN1 (calpain 1), CAPN2 (calpain 2) and CAPN3 (calpain 3), which have been implicated in limb-girdle muscular dystrophy." (PMID 37628820, 2023).
Marfan syndrome (1 paper, 2013). A disorder of the connective tissue. "In support of a specific role of calpain-2 in development of ascending AAs, a proteomics study of aortic media in patients with Marfan syndrome revealed a higher level of calpain-2 protein and calpain activity." (PMID 23977256, 2013). "A recent proteomic analysis study using aortic medial tissue protein extract from Marfan Syndrome patients showed upregulation of the C-terminal fragmentation of filamin A, that was highly correlated with elevated calpain-2 activity." (PMID 23977256, 2013).
meningioma (1 paper, 2018). A generally slow growing tumor attached to the dura mater. "Increased expression of CAPN1 has been observed in schwannomas and meningiomas and heightened expression of CAPN2, in colorectal adenocarcinoms." (PMID 30131853, 2018).
muscular dystrophy (1 paper, 2015). Muscular dystrophy (MD) refers to a group of more than 30 genetic diseases characterized by progressive weakness and degeneration of the skeletal muscles that control movement. "Deficiency in a calpain can lead to disease: platelet dysfunction (calpain-1), muscular dystrophy (calpain-3), stress-induced gastric ulcer (calpains 8 and 9), and calpain-2 deficiency is embryonically lethal." (PMID 26527411, 2015).
Myocardial fibrosis (1 paper, 2025). "Calpain-overexpressing mouse models have demonstrated cardiac enlargement and fibrosis, notably, in Tg-Capn2/tTA mice that develop DCM with chamber enlargement, myocardial fibrosis, and functional decline by 8 months of age." (PMID 41300744, 2025).
neuropathy (1 paper, 2024). A disorder affecting the nervous system that manifests with pain, tingling, numbness, and/or muscle weakness. "Calpain-2, in turn, has a role in neurodegeneration, and calpain-2 inhibition has been identified as a promising treatment for mitigating the effects of concussion-induced neuropathy." (PMID 38305737, 2024).
oesophageal cancer (1 paper, 2024). "Furthermore, in oesophageal cancer cells cis-platin targets calpain-1 (CAPN1) and calpain-2 (CAPN2)." (PMID 39097717, 2024).
osteoporosis (1 paper, 2022). A condition of reduced bone mass, with decreased cortical thickness and a decrease in the number and size of the trabeculae of cancellous bone (but normal chemical composition), resulting in increased fracture incidence. "PPIs could disturb Ca2+ homeostasis in the ER, increase [Ca2+]I, and activate the Calpain-2/Caspase-12 and Grp78/ATF4/CHOP pathways, ultimately triggering osteoporosis." (PMID 35183103, 2022).
Ovarian tumours (1 paper, 2012). "Ovarian tumours of the serous type were associated with high expression of calpastatin (χ2 = 23.755, d.f. = 4, P < 0.001), high calpain-1 (χ2=15.961, d.f. = 4, P = 0.003) and high calpain-2 (χ2 = 26.02, d.f. = 4, P < 0.001)." (PMID 22435971, 2012).
retinitis pigmentosa (1 paper, 2017). Retinitis pigmentosa (RP) is an inherited retinal dystrophy leading to progressive loss of the photoreceptors and retinal pigment epithelium and resulting in blindness usually after several decades. "The inhibition of calpain 2 is also benefit to relieving photoreceptor degeneration in retinitis pigmentosa." (PMID 29245980, 2017).
Stress urinary incontinence (1 paper, 2025). Involuntary urine leakage synchronous with exertion, or actions such as sneezing, or coughing. "MicroRNA-93 has also been found to regulate collagen I expression in fibroblasts via calpain-2 in stress urinary incontinence." (PMID 40731901, 2025).
T-cell leukemia (1 paper, 2025). A malignant disease of the T-lymphocytes in the bone marrow, thymus, and/or blood. "A study has revealed a link between Calpain-2 and human T-cell leukemia, showing decreased expression of Calpain-2 in this context." (PMID 39744572, 2025).
viral infection (1 paper, 2024). "Although participation of calpains in virus infections has not been well understood, several published studies indicate pro-viral functions of the host gene CAPN2." (PMID 38349185, 2024). "In order to determine the specific step of the replication cycle where CAPN2 functions to aid viral infection, we infected both WT and CAPN2 KO cells with VSV-SARS-CoV-2 and examined viral protein expression within a single replication cycle at 8 hpi using flow cytometry." (PMID 38349185, 2024). "We identified the host cysteine protease calpain-2 as an important positive regulator of the cell surface levels of SARS-CoV-2 cellular receptor ACE2 and, thus, a facilitator of viral infection." (PMID 38349185, 2024). "By either pharmacological inhibition or genetic knockout of calpain-2, the SARS-CoV-2 binding to host cells is blocked and viral infection is decreased." (PMID 38349185, 2024).
vitiligo (1 paper, 2022). Generalized well circumscribed patches of leukoderma that are generally distributed over symmetric body locations and is due to autoimmune destruction of melanocytes. "However, the expression of CAPN2 and CAPNS1 in vitiligo needs to be further explored." (PMID 35406685, 2022).
cancer (38 papers, 2014 to 2025). A tumor composed of atypical neoplastic, often pleomorphic cells that invade other tissues. "Several studies focusing on calpain 2 have implicated its expression and activity as crucial factors positively associated with cancer biology across various cancer types." (PMID 40151834, 2025). "A previous study has demonstrated that a calpain-2 inhibitor therapy could reduce colitis-associated cancer in murine models." (PMID 40109860, 2025). "Given that anchorage‐independent growth of cancer cells is strongly associated with invasiveness and metastasis, the isoform‐specific role of calpain 2 in cancer cell growth implies a potential connection between calpain 2 and the metastatic phenotype." (PMID 40151834, 2025). "Through correlation analysis, we observed that LAD1 expression levels were statistically associated with several cancer-related genes, including SFTPB, S100A6, CEACAM6, KRT19, S100A10, ANXA2, S100A11, and CAPN2." (PMID 41423496, 2025). "Calpain 2, a calcium‐dependent cysteine protease, exerts a wide‐ranging impact on tumorigenesis, cancer progression, tumor metastasis, and chemoresistance through the regulation of substrate protein activities and degradation." (PMID 40151834, 2025). "CNa 29, a calpain 2‐specific inhibitor, reduced cancer cell proliferation, decreased filamin A cleavage, downregulated TWIST1 expression, and significantly retarded metastasis." (PMID 40151834, 2025). "To assess the relationship between CAPN2 and cancer cell stemness, we analyzed the gene expressions of primary tumors and tumor spheroids." (PMID 40151834, 2025). "These previous studies highlighting the upregulation of calpain 2 in cancers underscore its potential as a promising therapeutic target in cancer treatment." (PMID 40151834, 2025). "Analysis of the GEPIA2 database revealed distinct expression patterns of GAS2 and Calpain-2 among various cancer patients." (PMID 39744572, 2025). "Dysregulated expression of calpain-2 is frequently observed in tumor cells and contributes to tumor suppression or progression in different types of cancers." (PMID 40109860, 2025). "A slight increase in calpain-2 expression promotes cancer progression through cleaving different tumor suppressors, while significant overexpression of calpain-2 induces apoptosis via cleaving a number of proteins necessary for cell survival." (PMID 40109860, 2025). "We propose that therapeutic intervention of calpain 2 isoform‐selective inhibition represents a promising strategy for preventing metastasis and treating this challenging type of cancer, TNBC." (PMID 40151834, 2025). "This aligns with previous findings that METTL16 can act as a tumor suppressor in some cancers, while CAPN2 drives tumor growth." (PMID 39434688, 2024). "In conclusion, we identified PIK3R1, CCND1, TERF2IP, SLC25A4, CAPN2, and TXN as potential markers associated with both cancer and MN." (PMID 38846934, 2024). "Cancer cell invasion is known to be regulated by Calpain-2-mediated cleavage of the focal adhesion and invadopodia-associated protein talin, leading to ameboid conversion of disseminated cells." (PMID 37736770, 2023). "To determine the expression level of CAPN2 in PC, we first used the open Gene Expression Omnibus (GEO) database, and The Cancer Genome Atlas (TCGA) dataset were used to analyze the mRNA expression of CAPN2 in PC." (PMID 35707527, 2022). "In various pathological states, abnormally elevated concentrations of calcium can activate CAPN2, which is involved in cellular signaling, cytoskeletal remodeling, cell survival, apoptosis, and cancer pathogenesis and progression." (PMID 35707527, 2022). "Next, the role of hnRNPK/LINC00263/miR-147a in the regulation of CAPN2 expression was verified in various cancer cells including DLD1, LoVo, A375, T98G, and A172 cells." (PMID 33731671, 2021). "Taken together, the hnRNPK/LINC00263/miR-147a/CAPN2 axis identified in this study represents a promising target for the treatment of human cancer." (PMID 33731671, 2021).
cancer (continued). "CAPN2 is a calcium-dependent protease and known to play an important role in the proliferation and metastasis of cancer cells.33,34." (PMID 33731671, 2021). "Taken together, our data suggest that hnRNPK/LINC00263/miR-147a/CAPN2 represents a promising target for the development of cancer therapeutics." (PMID 33731671, 2021). "Collectively, we demonstrate that hnRNPK-regulated LINC00263 plays an important role in cancer malignancy by acting as a miR-147a decoy and thus upregulating CAPN2." (PMID 33731671, 2021). "Human GAAP (hGAAP) has been reported to inhibit apoptosis and promote cell adhesion and migration via the stimulation of store-operated Ca2+ entry and calpain 2; the up-regulation of its mRNA has been observed in some human cancers." (PMID 25133526, 2014). "CAPN2 promoted cancer progression and chemotherapy resistance through the EGFR/AKT pathway." (PMID 41423496, 2025). "In addition, upregulation of CAPN1 (encoding calpain 1), another major isoform of calpain, did not affect any type of survival, underscoring the isoform‐specific role of calpain 2 in influencing the cancer prognosis of TNBC." (PMID 40151834, 2025). "Moreover, several factors have been identified as regulators of calpain 2 activity and expression in cancers." (PMID 40151834, 2025). "In addition, as our findings are specific to TNBC models, further research is required to evaluate the efficacy of calpain 2 inhibition as a therapeutic strategy in other cancer types to assess its broader applicability." (PMID 40151834, 2025). "Moreover, the non‐peptidomimetic calpain 2‐selective inhibitor, CNa 29, demonstrated a significant attenuation of cancer metastasis, accompanied by downregulation in proliferation, migration, and the EMT." (PMID 40151834, 2025). "Understanding these non-Calpain-2-dependent pathways could unveil novel therapeutic targets and broaden our strategies for cancer treatment." (PMID 39744572, 2025). "Furthermore, cancer stemness markers, such as Oct4, Nanog, and Sox2, were downregulated in CAPN2 knockdown cells." (PMID 40151834, 2025). "Targeting the GAS2-Calpain axis using these peptides could activate Calpain-2, thereby reducing abnormal protein accumulation and presenting a novel avenue for cancer therapy." (PMID 39744572, 2025). "Therefore, strategies aimed at increasing calpain-2’s gene expression and activity stand potential for cancer therapy." (PMID 40109860, 2025). "Interestingly, we observed a close relationship between CAPN2 expression and cancer stem cell (CSC) traits in HCC cells, evidenced by impaired sphere-forming and CSC-related marker expressions after CAPN2 knockdown, and verse vice." (PMID 39739077, 2024). "CAPN2 plays a major role in cancer-related cell proliferation." (PMID 38349185, 2024). "CAPN2 controls the malignant properties of cancer cells partly through ERK and p70S6K." (PMID 33731671, 2021). "Therefore, increased expression of LINC00263 in cancer cells suppresses the repressive effects of miR-147a, thereby increasing CAPN2 expression." (PMID 33731671, 2021). "Preventing nucleolar calpain-2 translocation would bring important insights into the precise role of this calpain, not only in the control of rRNA synthesis but also on other nucleolar targets and biological processes deregulated in cancer cells." (PMID 29507677, 2018). "Previous studies have reported that CAPN2 functioned as an oncogenic factor in human cancers." (PMID 29228653, 2017). "The calpain 2 (CAPN2) is upregulated in various malignant carcinomas." (PMID 29228653, 2017). "While a slight increase in calpain-2 expression might promote cancer progression through cleaving different tumor suppressors, a more significant increase in calpain-2 overexpression would induce apoptosis via cleaving a series of proteins necessary for cell survival." (PMID 40109860, 2025).
cancer (continued). "However, based on the observations shown in the present study and previous studies reported by others, we may suggest that inhibition of CAPN2 might sensitize cancer cells to the killing effects of some therapeutic drugs." (PMID 32382656, 2020). "CAPN2 knockdown inhibited the epithelial–mesenchymal transition (EMT), reducing cancer cell proliferation, migration, and invasion." (PMID 40151834, 2025). "Specifically, we aim to investigate how METTL16, an m6A writer gene, interacts with key downstream targets, such as CAPN2 and MROH8, to influence cancer metastasis." (PMID 39434688, 2024). "Without altering the protein level of calpain 2, CNa 29 retarded cancer cell growth in both 2D and 3D culture systems." (PMID 40151834, 2025). "MDA‐MB‐231 cells were treated with CNa 29 to determine whether pharmacological inhibition of calpain 2 by CNa 29 prevents filamin A cleavage‐induced HIF1α nuclear translocation, TWIST1 expression, EMT, cancer stemness, and metastasis." (PMID 40151834, 2025). "Our analysis led to the identification of PIK3R1, CCND1, TERF2IP, SLC25A4, CAPN2, and TXN as hub genes, which could potentially serve as targets for interventions in both MN and cancer." (PMID 38846934, 2024). "The ability of both calpain-2 and cathepsin B in inducing cell death is seen not only in CD-PCD but also in CI-PCD, making these two proteases potential targets for drug development in cancer therapy." (PMID 31969640, 2020). "CAPN2, ITPR1, PPP3CA, and PRKCA were enriched in calcium-induced T lymphocyte apoptosis pathway, and not reported on tumor-host immunological interactions, but those proteins were repeatedly reported relevant to human cancers." (PMID 31258820, 2019). "Additionally, while the interaction between GAS2 and Calpain-2 has been well-documented, it is imperative to explore potential alternative mechanisms through which GAS2 may exert its effects on cancer occurrence and progression." (PMID 39744572, 2025). "However, despite the involvement of calpain 2 in cancer biology, most studies failed to address specificity against different calpain isoforms or to provide insight into strategies for regulating isoform‐specific activity." (PMID 40151834, 2025). "Calpains2 (CAPN2) is a calcium-dependent, non-lysosomal cysteine protease that plays critical roles in normal cellular functions and pathological processes, including tumorigenesis, cancer progression, and metastasis." (PMID 35707527, 2022). "Moreover, specific inhibitors of PKA significantly impaired calpain activity developed upon LRP-1 silencing and we could show by coimmunoprecipitation that the level of serine phosphorylation of calpain-2 was decreased by the PKA inhibitor H-89, specifically in LRP-1 expressing carcinoma cells." (PMID 36052226, 2022).